CXCL12 (C-X-C motif chemokine ligand 12)
Diseases named in the same sentence as CXCL12 in open-access papers (continued):
Sharing a sentence is not in itself a finding about the gene and the disease.
Sepsis (32 papers, 2011 to 2025). Sepsis is defined as life-threatening organ dysfunction caused by a dysregulated host response to infection. "By integrating these components, we aim to provide a coherent framework for understanding the therapeutic potential and limitations of targeting CXCL12/CXCR4 in sepsis-associated ALI." (PMID 41614816, 2025). "In summary, although the CXCL12/CXCR4 axis is implicated in endothelial dysfunction in sepsis-induced ALI, its mechanistic contributions are less well characterized compared with its roles in immune and epithelial cell regulation." (PMID 41614816, 2025). "Collectively, miR-103a-3p heightens renal cell damage caused by sepsis by targeting CXCL12." (PMID 35510354, 2022). "The up-regulated expression of G-CSF in sepsis will reduce the concentration of BM CXCL12, which may cause the unstable of CXCL12/CXCR4 axis." (PMID 35006437, 2020). "The CXCL12/CXCR4 axis functions as a central regulatory hub in sepsis-induced acute lung injury (ALI), orchestrating the balance between inflammatory injury and tissue repair." (PMID 41614816, 2025). "Despite these insights, the specific regulatory roles of CXCL12/CXCR4 signaling in pulmonary vascular endothelial cells during sepsis-induced ALI remain incompletely defined." (PMID 41614816, 2025). "The present review examines the molecular and cellular mechanisms through which the CXCL12/CXCR4 axis shapes the course of sepsis-induced ALI." (PMID 41614816, 2025). "Accumulating evidence indicates that CXCL12 regulation in sepsis-induced acute lung injury (ALI) arises from the convergence of hypoxic, epigenetic, and cytokine-driven signals within the injured lung microenvironment." (PMID 41614816, 2025). "In summary, the present results emphasize a distinct miRNA-mediated enhancive mechanism for sepsis: miR-103a-3p alleviates sepsis-related AKI by regulating CXCL12." (PMID 35510354, 2022). "Sepsis decreased the levels of CXCL12 and stem cell factor (SCF) in the BM, while increasing SCF levels in the blood, which suggests a chemotactic gradient favorable for LSK and MEP egress into the blood." (PMID 35192546, 2022). "To investigate the mechanism of HSPC dynamic circulation during sepsis, we first analyzed the two well-known mediators of chemotaxis for HSPCs, CXCL12 and S1P." (PMID 30824730, 2019). "In support of this, a recent study of human septic patients revealed that CXCL12 levels were higher in patients with severe sepsis/septic shock as compared to healthy subjects." (PMID 29232699, 2017). "The data from our CLP model together with these clinical findings therefore lead us to conclude that engagement of the CXCR4/CXCL12 pathway is deleterious during sepsis." (PMID 29232699, 2017). "Immunoblotting of lung homogenates revealed that CXCL12 was strongly induced by sepsis and decreased by compstatin." (PMID 26337158, 2015). "Recently, the diagnostic value has been shown in neonatal sepsis, where elevated CXCR4 and CXCL12 levels were accompanied by increased sepsis severity." (PMID 26375818, 2015). "In contrast, activation of the CXCR4 seemed to have positive effects on such systemic and acute diseases as sepsis or polytrauma and, there is evidence that in vivo treatment with CXCL12 analogs results in improved survival." (PMID 26375818, 2015). "RT-qPCR was then used to determine CXCL12 expression post-sepsis induction." (PMID 35510354, 2022). "MiR-103a-3p was significantly repressed in the sepsis model, while CXCL12 was elevated." (PMID 35510354, 2022). "In sepsis, endothelial cells expressed lower Cxcl12 mRNA, and LepR+ cells expressed lower Scf mRNA." (PMID 35192546, 2022). "Interestingly, 3 out of 8 subjects with higher levels of CXCL12 (above 15 pg/ml) had bacterial superinfection or sepsis." (PMID 35087533, 2021). "Interestingly, a recent study of human septic patients revealed that CXCL12 levels were higher in patients with severe sepsis/septic shock as compared to healthy subjects." (PMID 29232699, 2017).
Sepsis (continued). "The finding that blocking the receptor (CXCR4) yields a result distinct from that observed when blocking the ligand (CXCL12) may suggest that one or more alternate binding partners is available and capable of modulating the response during sepsis." (PMID 29232699, 2017). "Also, in line with our results, administration of AMD3100 in combination with LPS was associated with an increased mortality in zebrafish and specific CXCL12 inhibitors revealed to be deleterious during sepsis induced by cecal ligation and puncture (CLP)." (PMID 27716214, 2016). "In summary, CXCL12/CXCR4 signaling regulates AT II cell migration, proliferation, and survival, thereby playing a pivotal role in alveolar epithelial repair during sepsis-induced ALI." (PMID 41614816, 2025). "Through these integrative mechanisms across immune and structural compartments, the CXCL12/CXCR4 axis orchestrates both injury and repair processes in sepsis-induced ALI, underscoring its potential as a compelling therapeutic target." (PMID 41614816, 2025). "We also found that CXCL12 induced FoxM1 expression in lung ECs via p110γ PI3K→ FoxO1 signaling and mediating endothelial regeneration in sepsis-induced inflammatory lung injury." (PMID 33804745, 2021). "In sepsis patients, a subset of CC motif chemokines, including CCL1, CCL2, CCL8, CCL20, or CXC motif chemokines that include CXCL8, CXCL10, and CXCL12, along with cytokines is increased compared to normal controls." (PMID 31583025, 2019). "Comparison of molecules between the control and sepsis groups revealed statistically significant differences, except for IFN-α, IL-1RA, IL-1β, IL-2, IL-6, IL-7, IL-15, LIF, GM-CSF, TNF-α, CCL4, CCL5, and CXCL12." (PMID 31583025, 2019). "Compared to the NC group, protein concentrations of CXCL-12, MMP-9, VEGF, TNF-α, and NO were significantly higher in the sepsis groups." (PMID 28513569, 2017). "We also observed that compstatin treatment efficiently reduced the expression of sepsis-induced chemokines involved in fibrocyte recruitment into tissues, including CCL2 (MCP1) and CXCL12." (PMID 26337158, 2015). "In summary, the CXCL12/CXCR4 signaling axis orchestrates the recruitment, retention, activation, and reverse migration of neutrophils, thereby shaping both the onset and progression of sepsis-induced ALI." (PMID 41614816, 2025). "Loss of ALKBH5 did not alter the levels of CXCL12 and CXCL5 in the plasma, bone marrow or peritoneal lavage fluid of mice in the steady state or during sepsis." (PMID 38114747, 2024). "Elevation of CXCL12 has been previously reported, but in the context of the rest of our findings, it can be hypothesized that CXCL12 is a plasma chemoattractant for VSELs and cEPCs in sepsis but not for HSPCs." (PMID 30824730, 2019). "Only a few studies have quantified CXCL12 or CXCR4 expression directly in human lung tissues or characterized temporal changes during disease progression, and interventional clinical data targeting this axis in sepsis or ALI are effectively nonexistent." (PMID 41614816, 2025).
asthma (31 papers, 2012 to 2025). "CXCL12 is known to aggravate asthma as it is associated with stimulation of eosinophilia, neovascularization, and attraction of progenitor cells and leukocytes in inflamed lungs." (PMID 36725964, 2023). "Collectively, HDAC4 deacetylates KLF5 to upregulate Slug and CXCL12, thereby causing airway remodeling and facilitating progression of asthma." (PMID 34118928, 2021). "The current study was undertaken to investigate the role of CXCL12 + 801 G/A SNP polymorphism in susceptibility to asthma in Iranian asthma patients." (PMID 24024210, 2013). "Moreover, further replication studies using a wider sample size and different population would be essential for further evaluation of the relationship between the CXCL12 genetic variations and the risk of asthma." (PMID 24024210, 2013). "Individuals with asthma showed a global reduction in alarmin and chemokine expression except CXCL12, which perhaps reflects their ongoing treatment regimen that is designed to reduce inflammation." (PMID 40399607, 2025). "Specific chemokines, such as CCL11, CCL5, and CXCL12, have been shown to play critical roles in airway inflammation in asthma by promoting the migration and activation of eosinophils and DCs, thereby driving excessive inflammatory responses in the airways." (PMID 41036310, 2025). "They confirmed an inverse relationship between miR-135b levels and CXCL12 expression in 68 pediatric asthma patients, linking elevated CXCL12 to bronchial hyper-reactivity and Th17-mediated inflammation." (PMID 40332077, 2025). "CXCL12/CXCR4 signaling was remarkedly up-regulated in asthma, predominantly bridging the interaction between fibroblasts and immune cell populations." (PMID 38317239, 2024). "We observed a significant upregulation of the chemokine CXCL12 in all subpopulations of fibroblast in the asthma model." (PMID 38317239, 2024). "This indicated that CXCL12/CXCR4 axis serves as a pivotal signaling pathway for fibroblast communication with immune cells that contributes to the pathogenesis of asthma." (PMID 38317239, 2024). "In the group of 68 pediatric patients with asthma, the reduction of miRNA-135b and the relationship of this molecule with the increase in CXCL12 (C-X-C motif chemokine ligand 12) were confirmed." (PMID 37511254, 2023). "CXCL12 has been reported to be increased in serum and broncho-alveolar lavage in asthmatics and is produced by the airway epithelium during asthma exacerbation." (PMID 36304163, 2022). "Of these, CXCR4, was found to be essential for fibrocyte recruitment in asthma, whereas its ligand CXCL12 was reported to be highly expressed in ESCC tissues." (PMID 35941662, 2022). "Further investigations are needed using LIT-927 or other neutraligands of CXCL12 to determine the impact of long-term treatment and to explore the possibility of treatment in tandem with existing asthma therapies, such as corticosteroids." (PMID 35831901, 2022). "For example, histone deacetylase 4 can mediate KLF5 deacetylation to upregulate CXCL12, leading to airway remodeling and promoting the progression of asthma." (PMID 35619697, 2022). "Increased levels of the chemokine CXCL12 has been found in the bronchoalveolar lavage of patients with asthma." (PMID 33571165, 2021). "In the current study, we explored the contributory role of HDAC4-mediated KLF5/Slug/CXCL12 axis in the development of asthma." (PMID 34118928, 2021). "We conducted this study aiming at exploring the effect of Histone deacetylase 4 (HDAC4)-mediated Kruppel-like factor 5 (KLF5)/Slug/CXC chemokine ligand-12 (CXCL12) axis on the development of asthma in regulation of airway inflammation and remodeling." (PMID 34118928, 2021). "Expression of CXCL12 in nasal mucosa of seasonal allergic rhinitis patients with asthma was up-regulated predominantly, compared with that in seasonal allergic rhinitis patients without asthma." (PMID 33836777, 2021).
asthma (continued). "In asthma patients, stimulation of bone marrow by an allergen leads to reduced expression of CXCL12 and CXCR4, possibly leading to outflow of immune cells from bone marrow." (PMID 32708315, 2020). "In a study on asthma patients, immunohistochemical staining of bronchial biopsy samples revealed that immunoreactivity of CXCL12 is highly correlated with vascularity." (PMID 32708315, 2020). "Increased immunoreactivity for CXCL12 in endothelial cells, macrophages, and T cells were detected in the airways of patients with asthma." (PMID 27309347, 2016). "A potential asthma therapeutic based on blocking of CXCL12 has been shown to reduce airway eosinophil recruitment in an ovalbumin mouse model of asthma." (PMID 26207385, 2015). "At baseline, CCL2 and CXCL12 were secreted differently from fatal asthma and non-asthma derived ASM in directions consistent with RNA-Seq results, but only those of CXCL12 were statistically significant." (PMID 26207385, 2015). "The results of this study also showed that the plasma level of CXCL12 was 312.53 ± 28.75 and 83.57 ± 6.74 pg/mL in asthma patients and healthy controls, respectively." (PMID 24024210, 2013). "An up-regulation of CXCR4 and CXCL12 was reported in inflammatory diseases, such as rheumatoid arthritis, multiple sclerosis, nephritis and asthma." (PMID 22511975, 2012). "Moreover, we cannot rule out the possibility that circulating SSEA-1+ cells express CXCR7 and compete for/exhaust binding of CXCL12, thereby decreasing airway inflammation and maintaining the epithelial barrier in asthma." (PMID 35670856, 2022). "Furthermore, previous studies demonstrated that CXCL12-neutralizing antibodies as well as CXCL12 neutralig can prevent the development of asthma." (PMID 34118928, 2021). "Targeting both PTGDR-1 and PTGDR-2 seems a valuable therapeutic approach to prevent flares in patients with SLE and in other diseases involving basophil, PGD2, and CXCL12 such as allergic diseases, chronic urticaria, asthma, inflammatory bowel diseases, and other chronic inflammatory disorders." (PMID 29463843, 2018). "Our RNA-Seq results for CXCL12 showing decreased mRNA levels in fatal asthma have an opposite effect from that expected based on increased CXCL12+ cell types in airway mucosa, but a direct comparison of these studies’ results is limited because of the different experimental designs." (PMID 26207385, 2015). "Therefore, this study was designed to explore the association between gene polymorphism at position +801 of CXCL12, known as SDF-1α3′A, and susceptibility to asthma in Iranian patients." (PMID 24024210, 2013). "We also showed an elevated level of CXCL12 circulating level in Iranian asthma patients." (PMID 24024210, 2013). "CXCL12 has been shown to participate in inflammatory response and airway remodeling in both OVA- and HDM-induced asthma models, while POSTN was confirmed to be upregulated in epithelial and subepithelial layers in bronchial biopsies of asthmatics." (PMID 38317239, 2024). "In contrast, miRNA-23a was reported to play a role in the occurrence of asthma by modifying B-cell lymphoma 2 (BCL2) expression in bronchial epithelial cells and C-X-C motif chemokine ligand 12 (CXCL12) in fibroblasts." (PMID 36675299, 2023). "And miR-23a is reportedly involved in the pathogenesis of asthma by targeting BCL2 in airway epithelial cells and CXCL12 in fibroblasts." (PMID 35927714, 2022). "The most influential nodes (Fn1, Igf1, Ccl2, C3, Timp1, Cxcl12, Ccl4, Ccr2, Spp1, C3ar1, Cat, Cyp2e1, Muc5ac, Muc5b) were selected for further validation in the OVA-induced asthma and post-asthmatic fibrosis murine model." (PMID 35625754, 2022). "In this part of the study, we constructed a mouse model of asthma induced by OVA and injected sh-HDAC4 and CXCL12 lentiviruses into the model mice via a tail vein." (PMID 34118928, 2021). "The CCL2, CCL13, CXCL12, and IL8 cytokine genes selected for experimental follow-up are known to be involved in asthma related processes." (PMID 26207385, 2015).
asthma (continued). "Follow-up qPCR and individual analyte ELISA experiments were conducted for four cytokines (i.e. CCL2, CCL13, CXCL12, IL8) to measure TNFα-induced changes by asthma status and vitamin D treatment." (PMID 26207385, 2015). "CXCL12, which belongs to the CXC chemokine subfamily, participates in inflammatory reactions and is found to accelerate fibrocyte transmigration in patients with chronic obstructive asthma and in asthma patients during an acute exacerbation." (PMID 34118928, 2021). "The pro-inflammatory chemokine ligand 12 (CXCL12) binds to CXCR4 and has previously been shown to recruit numerous cell types such as lymphocytes, monocytes, and eosinophils into the lung airway fluid (BALF) of asthma patients." (PMID 32759853, 2020). "Cytokine-mediated regulation of CXCL12 has been demonstrated in eosinophils and lung epithelial cells; the effects of CXCL12/CXCR4 axis showed a contribution to the inflammatory response in a murine model of asthma." (PMID 24024210, 2013). "Chalcone 4 blocks responses of CXCR4 to CXCL12 in vitro without affecting the basal level receptor activity and displays anti-inflammatory effects in a murine model of asthma in vivo." (PMID 23449983, 2013). "Accumulating evidence also suggests that CXCL12/CXCR4 signaling plays an important role in shaping the microenvironment, mediating allergic airway inflammation (such as retaining neutrophils at inflammatory sites) and promoting airway remodeling (e.g., induction of EMT) in asthma." (PMID 38317239, 2024). "Plasma CXCL12 seems not increased in other eosinophil related pathology such as asthma, suggesting that it may be specific for EoE." (PMID 37006253, 2023). "Further, airway mucosa from asthma patients had a greater number of CXCL12 (aka SDF1) positive cells than that from healthy subjects, and the number of CXCL12+ cells correlated with vascularity, suggesting that CXCL12 may play a role in airway remodeling." (PMID 26207385, 2015). "Thus, consistency between mRNA and protein secretion levels is high for TNFα-induced changes, and present to varying degrees among the four cytokines for changes between fatal asthma- and non-asthma-derived ASM, with CXCL12 and IL8 showing the greatest consistency and CCL13 the weakest." (PMID 26207385, 2015). "We found that TNFα treatment induced CCL2, CCL13, and IL8 mRNA expression in most fatal asthma- and non-asthma-derived ASM samples, but TNFα treatment did not induce CXCL12." (PMID 26207385, 2015). "Fatal asthma-derived ASM secreted greater TNFα-induced IL8 and lower TNFα-induced CXCL12 as compared to non-asthma-derived ASM, while TNFα-induced CCL2, and CCL13 levels between fatal asthma- and non-asthma-derived ASM were not significantly different." (PMID 26207385, 2015). "We chose to focus our functional studies on four cytokines that were differentially expressed between fatal asthma- and non-asthma-derived ASM and were also modified by vitamin D treatment in fatal asthma-derived ASM (i.e., CCL2, CCL13, CXCL12, IL8)." (PMID 26207385, 2015). "Based on our results, CCL2, CXCL12, and IL8 may have correlated mRNA and protein secretion levels that differ between fatal asthma- and non-asthma-derived ASM, but the difference in IL8 may only be noticeable with TNFα induction due to its low baseline levels." (PMID 26207385, 2015). "However, the eosinophil population was not preponderantly impacted by the blockade of the CXCL12/CXCR4 axis, unlike in asthma and AESGF." (PMID 22511975, 2012). "Interestingly, CXCL12 expression remained at baseline after 3 weeks of HDM exposure; previous studies have shown that airway remodeling is not yet established at this time point and may not occur at all in milder cases of asthma." (PMID 35831901, 2022).